HIF1A (hypoxia inducible factor 1 subunit alpha)
Diseases named in the same sentence as HIF1A in open-access papers (continued):
Sharing a sentence is not in itself a finding about the gene and the disease.
cancer (continued). "Furthermore, TXNIP is implicated in many other pathways, including the HIF1α hypoxic pathway, the IL-dependent pathway, the B cell receptor (BCR) signaling pathway, and the NF-κB signaling pathway, all of which require empirical support to comprehend TXNIP’s role in cancer." (PMID 36366411, 2022). "The activated PI3K/Akt pathway plays an important role in human cancer, and activated PI3K/Akt signaling up-regulates HIF1A transcription and translation." (PMID 34998404, 2022). "Recent system biology studies have proposed that the coexistence of upregulated HIF-1α and activated AMPK are indicative of increased glycolysis and OXPHOS in cancer cells with a hybrid state of metabolism." (PMID 36591481, 2022). "It has been reported that drug resistance can be prevented in cancer cells by inhibiting the Ras/Raf/MEK/ERK, PI3K/AKT pathways, and key transcription factors, such as NF-κB and HIF-1α." (PMID 35473537, 2022). "HIF-1α is critical for cancer stem cell maintenance, as knockdown of HIF-1α in cancer stem cells leads to reduce self-renewal capacity, increases apoptosis, and attenuates tumorigenesis." (PMID 36014432, 2022). "Given the basic role of HIF-1α in the presence of hypoxia, which leads to tumorigenesis, several HIF-1α inhibitors were developed to efficiently treat cancer." (PMID 36014432, 2022). "Nevertheless, the failure rate is high with HIF-1α inhibitors, which points out the need to delineate precise molecular mechanisms by which HIF-1α impacts cancer cells." (PMID 35681691, 2022). "In this study, we predicted HIF-1α and ANGPT2 as regulators of HCC by the OncoMir cancer database and showed a strong positive correlation with HIF-1α and ANGPT2 gene expression in HCC patients." (PMID 35163556, 2022). "Hypoxia-induced HIF1A promotes EMT by enhancing the snail, β-catenin and Notch signaling pathways, leading to cancer cell survival, cancer metastasis and resistance to immune attack." (PMID 35659268, 2022). "Analysis of ENCORI pan cancer co-expression demonstrated a positive correlation between KDM4A mRNA and HIF1α mRNA level in CC tissues." (PMID 35287356, 2022). "One of these theories, the reverse Warburg effect, theorizes that cancer cells can create a pseudo-hypoxic microenvironment in the stroma, inducing MCT4 upregulation and increased glycolysis in stromal fibroblasts through HIF-1α activation." (PMID 35626155, 2022). "Hypoxia and HIF1α activate Wnt/β-catenin signaling via the expression of BCL9, resulting in cancer cell proliferation and metastasis." (PMID 35027586, 2022). "Transcriptionally, LDHA is regulated by forkhead box protein M1 (FOXM1), hypoxia-inducible factors (HIF-1α and HIF-2α), Jumonji C Domain 2A (JMJD2A), and peroxisome proliferator-activated receptor gamma (PPAR-γ) coactivator 1-beta (PGC1β) in cancer cells." (PMID 35832094, 2022). "Current research suggests that HIF1α, as one of the most important members of the HIF family, is closely related to the occurrence, development, and prognosis of cancers." (PMID 35860430, 2022). "Metformin has displayed anticancer effects towards different types of cancer cells in an in vitro cell study, with Nrf2, YAP, HIF-1α, HMGB1, TGF-β1, glycolysis and glutamine metabolism being proposed action targets at a cellular level." (PMID 36012397, 2022). "Over the past years, HIF1A, EPAS1, and VEGFA have been highlighted to be attractive potential targets for anti-cancer therapies." (PMID 36230822, 2022).
cancer (continued). "In this study, our data demonstrated that PC formation regulates cancer cell viability and growth by NPHP3 expression through ROS-induced ERK activation and HIF-1α stabilization under SD conditions." (PMID 36498831, 2022). "Therefore, blocking both PD-L1 and HIF-1α may be a promising approach for cancer immunotherapy." (PMID 36226050, 2022). "In particular, the cancer pathway, microRNAs in cancer, PI3K-Akt signaling pathway, and HIF1A signaling pathway were enriched in the analysis of transcriptome sequencing." (PMID 35774500, 2022). "Isoflurane activated the expression of HIF-1α and its downstream effectors in prostate PC3 cancer cells, leading to increased migration." (PMID 35222023, 2022). "PKM2 promotes transcription of target genes such as GLUTs, LDH-A, and HIF-1α-targeted expression of VEGF-A, thereby promoting cancer cell growth and positive feedback regulation of glycolysis." (PMID 36612063, 2022). "At the transcriptional level, oncogenic transcriptional factors c‐Myc and HIF1α induce multiple glycolytic enzymes expression, such as GLUTs, HKs, LDHA and PKM2, rendering metabolic reprogramming of cancer cells." (PMID 36229913, 2022). "HIF-1, a heterodimer of HIF-1α and HIF-1β, plays the most prominent role in oxygen homeostasis and cancer progression." (PMID 35681691, 2022). "Seven anti-HCC core targets (CASP3, EGFR, ERBB2, mTOR, MMP9, HIF1A, and PPARG) followed the pathways in cancer." (PMID 35959427, 2022). "NF-ƙB, EGFR, PTEN/PI3K/AKT, Wnt, HIF-1α, STAT3 and AKT/ERK/mTOR signaling pathways are among those being influenced by dysregulation of miR-671 in different cancers." (PMID 36545507, 2022). "The HIF1A and EPAS1 expression levels were higher in benign lesions compared to malignant tumors (p = 0.04067 and p = 0.0228, respectively)." (PMID 36230822, 2022). "It has been reported that hypoxia, through HIF-1α, induces the up-regulation of CXCR4 in TAMs but also in endothelial and cancer cells; this axis regulates the migration of the different cells that integrate the TME." (PMID 35565420, 2022). "The crosstalk between oncogene and tumor suppressor transcription factors such as NF-kB, STAT3, HIF-1α, and NRF2, is the mechanism of inflammation-driven cancer." (PMID 35967354, 2022). "In conclusion, we found IRF1 to be a general predictor for CD274 expression in all three studied cancer types, and STAT1, NFKB, HIF1A and BRD4 to be predictors for some of these cancer types." (PMID 35289334, 2022). "The network results demonstrated that seven anti-HCC core targets (CASP3, EGFR, ERBB2, mTOR, MMP9, HIF1A, and PPARG) followed the pathways in cancer (degree 7)." (PMID 35959427, 2022). "mPRα knockdown in A549 and PC-9 cells significantly inhibited STAT3 phosphorylation, as well as HIF1α and VEGF protein levels, decreasing cancer cell migration and invasion." (PMID 35123491, 2022). "The regulation of lactate by c-Myc and HIF-1α in tumors can also be achieved by the induction of MCT; c-Myc induces MCT1306,307, and HIF-1α induces MCT1 and MCT4308, the major lactate transporters utilized by cancer cells." (PMID 36050306, 2022). "Cancer-derived extracellular succinate enhances cancer cell and macrophage migration through SUCNR-1 → PI-3 K → HIF-1α pathway." (PMID 36344992, 2022). "The PDH activity is inhibited if the enzyme is phosphorylated by its regulatory kinases PDKs and, in cancer cells, PDK1 is transcriptionally induced by HIF1α." (PMID 35163570, 2022). "HIF-1α and HIF-2α differ in how they regulate the highly oncogenic pathway, MYC, which is seen to be upregulated or downregulated in cancers by up to 70%." (PMID 35267567, 2022). "HIF-1α/BNIP3 mediated mitophagy is an important pathway for treating myocardial ischemia, cancer, and chronic inflammatory diseases." (PMID 35865944, 2022).
cancer (continued). "Hypoxia-inducible factor-1alpha (HIF-1α) is a major transcription factor that adapts to low oxygen homeostasis and regulates the expression of several hypoxic genes, which aid in cancer survival and development." (PMID 35592530, 2022). "Our data demonstrated that PC formation regulated cancer cell viability under SD condition via NPHP3 expression by ROS-induced ERK activation and HIF-1α stabilization." (PMID 36498831, 2022). "It is a promising inhibitor of STAT3 and represses cancer angiogenesis via blocking the action of STAT3 and the expression of VEGF and HIF-1α." (PMID 35355732, 2022). "In conclusion, apigetrin induces anti-cancer effects by regulating AKT, a key transmitter of HIF-1α and AR signaling in PCa cells." (PMID 35740392, 2022). "Mechanistically, this was driven through a β2-adrenergic receptor—HIF1α—Snail axis, as HIF1α knockdown prevented EMT in cancer cells." (PMID 36074318, 2022). "HIF1A and STAT3 cooperatively regulate IL-10 transcription via HRE I and HRE II regions to exacerbate autoimmune diseases and cancer metastasis." (PMID 35659268, 2022). "In addition, HIF1A transcription is also regulated and more recent evidence indicates that the regulation of HIF1A mRNA translation is a crucial element of HIF1α induction under hypoxia and stress conditions, making the translational machinery an important target for cancer therapy." (PMID 35629169, 2022). "The authors analyzed the effect of BaP (1.5 or 25 μM) exposure on A549 and MCF-7 cancer cells and observed induction of ROS and modulation of HIF-1α and HO-1 in A549 and MCF-7 cancer cells." (PMID 35209168, 2022). "The TGFβ superfamily members can stimulate cytokine-inducible factors, including HIF1a, C-X-C motif chemokine ligands (CXCLs), and VEGF, in cancer cells." (PMID 35280749, 2022). "For example, an interaction between HIF-1α and LOXL2 (lysyl oxidase like 2) in hepatocellular carcinoma promoted cancer development, and increased angiogenesis and the EMT." (PMID 36619866, 2022). "HIF1α, as well as phosphoinositide 3-kinase/protein kinase B/mammalian target of rapamycin (PI3K/Akt/mTOR) pathways are crucial regulators of cancer cell proliferation and glycolytic metabolism." (PMID 35163570, 2022). "We found that expression of HIF1A and EPAS1 was higher in controls and VEGFA higher in patients with malignant tumors." (PMID 36230822, 2022). "Therefore, HIF-1α may be an important therapeutic target in cancer." (PMID 35681691, 2022). "In this cancer, SIRT1 deacetylates HIF-1α at lysine 674 inhibiting the interaction between this transcriptional factor and p300, thereby maintaining an epithelial-like phenotype." (PMID 35745656, 2022). "The glycolytic enzyme PGK1 is involved in the HIF1α transcription factor network, in which PGK1 together with pyruvate kinase M2 (PKM2) controls the ATP production during aerobic glycolysis in cancer cells (also known as the “Warburg effect”)." (PMID 36038612, 2022). "We therefore set out to quantify to what extent the PD-L1 mRNA level (CD274) in cancer patients can be predicted by activity of the relevant TFs MYC, HIF1A/2A, JUN, IRF1, STAT1/3, NFKB, and NRF2." (PMID 35289334, 2022). "HNK reduced the expression of HIF-1α, GLUT1, HK2 and PDK1, decreased ECAR, increased OCR, and decreased glucose uptake, lactate production and ATP production in cancer cells." (PMID 35350760, 2022). "HIF-1α is the pivotal moderator of hypoxia-related responses that promote abnormal angiogenesis and MDR in several cancer subtypes." (PMID 36153528, 2022). "We recently identified an lncRNA, namely, HIF-1α inhibitor at transcription level (HITT), that is commonly decreased in many types of cancer." (PMID 35909936, 2022).
cancer (continued). "We also noticed an increased occupancy of the HIF1α promoter by KDM6B, suggesting its regulatory role in maintaining hypoxia in detached cancer cells." (PMID 35186918, 2022). "Considering our results, the expression of HIF1α, VEGF, and NF-κB is upregulated in HCC, which promotes cancer cell migration and induces angiogenesis." (PMID 36092163, 2022). "Analyzing the GOI expression when subgroups were based on the Youden’s J statistic for age, we observed significantly elevated levels of both HIF1A (p = 0.0023) and EPAS1 (p = 0.0246) between controls and cancer patients in the group > 56 yrs." (PMID 36230822, 2022). "Further, in these two types of cancers, TGF-β increased the expression of HIF-1α and HIF-2α as well." (PMID 35625561, 2022). "In turn, the overexpression of SIRT1 stabilizes the hypoxia-inducible factor 1-alpha (HIF-1α) protein, leading to glycolysis reinforcement in cancer cells." (PMID 36139487, 2022). "There are numerous small molecule drugs that inhibit different parts of the HIF-1α signaling pathway, but the clinical efficacy of HIF-1α inhibitory drugs in cancer have been limited thus far." (PMID 35634282, 2022). "Despite that, the drug market lacks safe and efficacious anti-HIF-1α molecules, raising the quest for fully unveiling the complex interactome of HIF-1α in cancer to discover more effective strategies." (PMID 35681691, 2022). "MiR-20b has also been described as an oncogenic miRNA by regulating the expression levels of hypoxia-inducible factor-1 alpha (HIF-1α) and vascular endothelial growth factor (VEGF) in various cancer types." (PMID 35517859, 2022). "Further, the expression of HIF-1α and the activity of HIF pathway can also be upregulated by DNA methylation in cancer." (PMID 36319992, 2022). "CAF-mediated TGF-β signaling synergizes with HIF-1α signaling and enhances the expression of GLI2 in cancer cells, inducing stemness." (PMID 36010899, 2022). "Since both HIF-1 and A3AR have been found to be overexpressed in cancer, a link between A3AR stimulation and the modulation of HIF-1α expression in hypoxic conditions has been explored." (PMID 34750517, 2022). "Firstly, ROS have been shown to activate PI3K/Akt/mTOR signaling cascade in different cancer cell lines (MCF-7, HepG2, H-1299, PC-3), enhancing HIF-1α and VEGF expression and ultimately angiogenesis." (PMID 36359304, 2022). "In addition to the endeavors to translate HIF-1α antisense oligonucleotides into cancer therapy, several approved chemotherapeutics such as camptothecins, rapamycin analogs, and anthracyclines have been tested clinically for their indirect HIF-1α inhibitory action in various cancers." (PMID 35681691, 2022). "On the contrary, ILTPs function to control cancer cell metastasis and proliferation by regulating the expression of VEGF, HIF-1α, and COX-2 under the influence of angiogenesis." (PMID 35321703, 2022). "Bevacizumab-induced hypoxia stimulates the up-regulation of HIF1-α and consequently of CD39 and CD73 in cancer cells, leading to suppression of cytotoxic T lymphocytes (CTLs) and NK cells." (PMID 36432658, 2022). "Potentiation by acidic pHe and involvement in HIF-1α regulation demonstrates the interest of cancer cells in keeping TRPC5 channels active and over-expressed, in order to promote cancer-specific hallmarks, in particular chemoresistance." (PMID 35806388, 2022). "It improves the stabilization of HIF-1α and upregulates adenosine monophosphate–activated protein kinase (AMPK), as the main regulator of cancer cells’ growth and proliferation." (PMID 36292613, 2022). "First, the accumulation of HIF-1α can induce the expression of glucose transporter-1 (GLUT1) and enhance glucose uptake by cancer cells." (PMID 35350760, 2022). "Several transcription factors, such as STAT1/3, HIF-1α, NF-κB, AP1, and MYC, and various cytokines, including IFN-γ, and TGF-β, have been shown to regulate the expression of the PD-L1 gene in cancer cells." (PMID 35626102, 2022).
cancer (continued). "Recent in vivo studies revealed that SQAP induced the degradation of HIF-1α and then decreased the expression of histone deacetylase (HDAC), which is related to the abnormal proliferation of cancer cells." (PMID 34738103, 2022). "The key finding of this study is that MAGED2 is required under both physical hypoxia and treatment with the hypoxia mimetic CoCl2 to fully induce HIF-1α in renal (HEK293) and cancer (HeLa) cell culture models." (PMID 36359819, 2022). "The function of the proteins overexpressed in cancer, such as CAIX, PDK, BNip3, Mxi-1, VEGF, and EPO, is regulated by HIF-1a in acute hypoxia." (PMID 36294785, 2022). "Hypoxia-inducible factor-1alpha (HIF-1α), the primary regulator of cell response to hypoxia, has the function to increase proliferation and drug resistance of some cancers including BC via regulating metabolic enzymes." (PMID 36119505, 2022). "It is well accepted that hypoxia-inducible factor (HIF) is elevated in residual carcinoma cells after RFA, including HIF-1α and HIF-2α." (PMID 36212390, 2022). "Hypoxia-induced HIF-1α can also stimulate the MCT4 promoter and increase its expression in the carcinoma cell lines." (PMID 36612084, 2022). "Both HIF-1α and caspase-3 expressions in 70 PTC samples and their relatively normal para-carcinoma tissues were detected by IHC." (PMID 36329448, 2022). "In summary, our data demonstrate that targeting HIF-1α with BAY 87-2243 has effects on both fibroblasts and carcinoma cells in co-culture." (PMID 35814364, 2022). "The transmission of HISLA from TAM to cancer cells restrains the hydroxylation via a reduction of the binding between PHD2 and HIF-1α, and stabilizes the latter." (PMID 34900986, 2021). "Accumulated evidence introduced here showed that phytochemicals can be used as potent HIF-1α inhibitors and that the suppression of HIF-1α can reinforce the efficiency of cancer treatments, such as chemotherapy and radiation therapy." (PMID 34575983, 2021). "Mechanistically, it was confirmed that HIF-1α is regulated by both mTOR and ERK pathways in hypoxic cancer cells following vanillic acid treatment." (PMID 34575983, 2021). "Thus, targeting HIF1α may serve as a promising modality in cancer treatment." (PMID 34686682, 2021). "It was shown that HSP27 interacts with HIF-1α, while HIF-1α and HSF1 regulate HSP27 expression in cancer cells." (PMID 33806538, 2021). "As HIF1α inhibits pyruvate dehydrogenase (PDH) which converts pyruvate to acetyl-CoA, Gln is essential for the maintenance of the integrity of TCA cycle in cancer cells by refilling the mitochondrial carbon pool." (PMID 34924566, 2021). "Similar to other master regulators when deregulated, both HIF-1α and HIF-2α can drive pathologies, in particular tumorigenesis and cancer progression." (PMID 33466454, 2021). "The relationship between the expression of HIF-1A and microvessel density (MVD) has mainly been investigated in many cancers, including GBC 13-15." (PMID 33403040, 2021). "Albendazole has been repurposed as a potential chemotherapeutic agent in cancer patients where it inhibited vascular endothelial growth factor (VEGF) and HIF-1α leading to reduced angiogenesis." (PMID 34075120, 2021). "While our results stress that hypoxia/ HIF1α/ANG axis has a great impact on mature tRNA-His-GTG cleavage, which suggested that the cancer cells produced more 5’tiRNA-His-GTG under the external stimulation of hypoxia." (PMID 33588913, 2021). "Thymoquinone was observed to destabilize HIF-1α by hindering the interaction of HIF-1α with HSP90, ultimately promoting the apoptosis of hypoxic cancer cells." (PMID 34575983, 2021). "Overall, our results indicate a critical regulatory role of HIFAL in HIF-1α-driven transactivation and glycolysis, identifying HIFAL as a therapeutic target for cancer treatment." (PMID 33637716, 2021).